AKR1B1 (aldo-keto reductase family 1 member B)
Diseases named in the same sentence as AKR1B1 in open-access papers (continued):
Sharing a sentence is not in itself a finding about the gene and the disease.
pancreatic cancer (8 papers, 2009 to 2025). "In a study, it has been shown that the expression level of Aldo-keto reductase family 1 member B1 (AKR1B1) in pancreatic cancer cells is associated with an increased level and release of exosomes from tumor cells." (PMID 37287924, 2023). "Further research is required to elucidate the exact mechanism underlying the AKR1B1 role in tumour progression in pancreatic cancer." (PMID 32633024, 2020). "Interestingly, AKR1B1 overexpression was associated with decreased survival in patients with pancreatic cancer." (PMID 32633024, 2020). "In pancreatic cancer, AKR1B1, upregulated by the β2-adrenergic receptor, promotes proliferation and inhibits apoptosis." (PMID 40361399, 2025). "Studies have shown that ADRB2 can directly interact with and upregulate AKR1B1 in pancreatic cancer cells, promoting cell proliferation and inhibiting apoptosis through the ERK1/2 pathway." (PMID 34646828, 2021). "AKR1B1 alongside B2‐AR has been shown to be expressed more in the cytoplasm of pancreatic cancer cells while a moderate expression of AKR1B1 and B2‐AR in the nucleus and the membrane of cells has been demonstrated." (PMID 32633024, 2020). "For example, induction of AKR1B1 which could reduce DRC to Daunorubicinol induced resistant to tumour cells in pancreatic cancer." (PMID 32633024, 2020). "Consequently, AKR1B1 overexpression was shown to result in inhibition of apoptosis and proliferation induction in pancreatic cancer." (PMID 32633024, 2020). "Lower levels of AKR1B1 was seen in mice with pancreatic tumours after knockdown of ZEB1 in comparison with controls; however, no direct effect was found between AKR1B1 and ZEB1 suggesting an indirect interaction." (PMID 32633024, 2020).
asthma (6 papers, 2011 to 2025). "The putative association between allergic rhinitis and asthma with AKR1B1 variants was reported." (PMID 34876009, 2021). "AKR1B1 plays an important role in different inflammatory diseases such as atherosclerosis, sepsis, asthma, uveitis, and colon cancer." (PMID 27540362, 2016). "In mice, AKR1B1 inhibition reduced airway inflammation, hyperresponsiveness and IgE and Th2-cytokine levels in ovalbumin and ragweed pollen extract-induced asthma." (PMID 27540362, 2016). "Furthermore, studies in AKR−/− mice also support a role of AKR1B1 in the pathogenesis of asthma and allergic rhinitis." (PMID 27540362, 2016).
ovarian carcinoma (6 papers, 2019 to 2023). A malignant neoplasm originating from the surface ovarian epithelium. "The binding of (−)-KU with AKR1B1 causes downregulation of AKR1B1 and its downstream proteins (PKC, NF-kB, AKT, Nrf2, COX2, and Twist2) in ovarian cancer cells." (PMID 37959760, 2023). "Other reports have revealed that AKR1B1 protein levels are significantly upregulated in fibroblasts cocultured with ovarian cancer cells and also in ovarian cancer." (PMID 35159076, 2022). "We found that (±)KU exhibited a cytotoxic effect that was significantly stronger than zopolrestat (ZP) and epalrestat (EP) (known AKR1B1 inhibitors) on breast and ovarian cancer cells." (PMID 36552555, 2022). "The expression levels of carboplatin resistance-associated proteins, AKR1B1, ITGAV, TGFβ1 and G6PD, in platinum resistant and relapsed human ovarian cancer samples are consistent with our observations in vitro data on control and carboplatin-resistant cells." (PMID 36463238, 2022). "Breast and ovarian cancer cell lines with different subtypes were detected to have AKR1B1 protein levels by Western blotting." (PMID 36552555, 2022). "Growing recent evidence has suggested that AKR1B1 is overexpressed in various human cancers, such as colon, liver, pancreas, lung, prostate, cervix, breast and ovarian cancer." (PMID 36552555, 2022). "AKR1B1 expression is increased in rectal, hepatocellular, lung, breast, cervical, and ovarian cancer and decreased in colorectal and endometrial cancer." (PMID 35159076, 2022). "In our study, elevated levels of AKR1B1 and ALDH5A1 in post-NACT treated tumors suggests alterations in proteins regulating cellular metabolism accompanies exposure of ovarian cancer cells to cytotoxic chemotherapy." (PMID 36195845, 2022). "In the ovarian cancer cell group, NS cell lines (A2780 and SKOV3 cells) revealed an AKR1B1 protein higher than the high-grade serous ovarian cancer cell lines (OVCAR3 cells), and SKOV3 cells showed the highest AKR1B1 level." (PMID 36552555, 2022). "Until now, no study has assessed AKR1B1 and AKR1B10 levels using IHC in a large cohort of ovarian cancer patients." (PMID 35159076, 2022).
glioblastoma (4 papers, 2023 to 2025). The most malignant astrocytic tumor (WHO grade IV). "AKR1B1 genetic deletion or pharmacological inhibition reduced fructose production, leading to impaired proliferation and migration in A549 (lung) and U87 (glioblastoma) cells." (PMID 41154825, 2025). "Limitations of the study include the need for more extensive investigations into the role of AKR1B1 in promoting cancer growth across various cancer types, beyond lung adenocarcinoma and glioblastoma, to determine its universality." (PMID 39406918, 2024). "AKR1B1 expression was quantified in normal human astrocytes, glioblastoma multiforme (GBM) cell lines, and normal tissues by using quantitative real-time polymerase chain reaction." (PMID 37185746, 2023). "In addition, the results showed that AKR1B1, AKR1C2, and AKR1C3, which were also members of the aldosterone reductase family, were also involved in the mechanism of the resistance of glioblastoma to adriamycin." (PMID 37173953, 2023).
glioma (4 papers, 2021 to 2024). A benign or malignant brain and spinal cord tumor that arises from glial cells (astrocytes, oligodendrocytes, ependymal cells). "In human glioma cells, high expression of AKR1B1 was found to be associated with the upregulation of NORAD (non-coding RNA activated by DNA damage)." (PMID 39055885, 2024). "The MTT assays showed that AKR1B1 overexpression inhibited glioma cell proliferation whereas AKR1B1 knockdown increased it." (PMID 37185746, 2023). "The AKR1B1 level was also decreased in glioma cell lines such as T98G and 8401 in comparison with that in human astrocytes." (PMID 37185746, 2023). "Among normal human astrocytes (SV-1) and human glioma cell lines (U87, 8401, G5T, 05MG, and T98G), 8401 and T98G cell lines presented the lowest AKR1B1 mRNA levels." (PMID 37185746, 2023). "According to our findings in human tissues, human glioma cell lines with low AKR1B1 expression should be selected as the appropriate cell model." (PMID 37185746, 2023). "According to the analysis by quantitative reverse-transcription polymerase chain reaction, the AKR1B1 mRNA level significantly decreased by 50% in human glioma tissues, suggesting that low AKR1B1 levels participated in tumorigenesis." (PMID 37185746, 2023). "Given that AKR1B1-expressing glioma cells inhibited cell growth and induced activation of p38 MAPK signaling, the p38 MAPK pathway has been shown to play a role in inducing apoptosis or programmed cell death in cancer cells." (PMID 37185746, 2023). "In this study, we aimed to investigate the roles of AKR1B1 in glioma cell proliferation and related mechanisms." (PMID 37185746, 2023). "In our study, AKR1B1 overexpression increased the caspase-3/7 activity of glioma cells, suggesting that AKR1B1 is a potential therapeutic effect of gliomas." (PMID 37185746, 2023). "This study aimed to investigate the regulatory role of Aldo-keto reductase family 1 member B1 (AKR1B1) in glioma cell proliferation through p38 MAPK activation to control Bcl-2/BAX/caspase-3 apoptosis signaling." (PMID 37185746, 2023). "This study demonstrated that AKR1B1 was significantly decreased in glioma tissues compared with that in the adjacent tissues." (PMID 37185746, 2023). "AKR1B1 expression was significantly downregulated in glioma tissues and GBM cell lines (T98G and 8401)." (PMID 37185746, 2023). "In the present study, AKR1B1 expression was significantly decreased in glioma tissues compared with that in adjacent normal tissues." (PMID 37185746, 2023). "Glioma cell proliferation was inhibited by AKR1B1 overexpression but was slightly increased by AKR1B1 knockdown." (PMID 37185746, 2023). "In conclusion, AKR1B1 regulated glioma cell proliferation through the involvement of p38 MAPK-induced BAX/Bcl-2/caspase-3 apoptosis signaling." (PMID 37185746, 2023). "It regulates the expression of genes associated with metabolic pathways, such as aldo-keto reductase family 1 member B1 (AKR1B1), which mediates the cytotoxicity of 2-deoxyglucose, thereby promoting the progression of glioma." (PMID 37998733, 2023). "For example, in glioma cells, it has been shown that the association of NORAD and AKR1B1 activates the ERK pathway, promoting a malignant phenotype." (PMID 33739352, 2021). "Therefore, AKR1B1-induced p38 MAPK phosphorylation through sorbitol in glioma cells is the focus of our future research." (PMID 37185746, 2023). "To test our hypothesis, we knocked down AKR1B1 in glioma cells through si-RNA and measured cell viability every 24 h." (PMID 37185746, 2023). "Based on our observations, we speculate that the low expression of AKR1B1 may involve glioma progression." (PMID 37185746, 2023). "Considering that caspase-3/7 plays a major role in cell apoptosis, we next examined whether caspase-3/7 could be activated in AKR1B1-expressing glioma cells." (PMID 37185746, 2023).
glioma (continued). "We hypothesized that the AKR1B1 reduces glioma cell proliferation and activates p38 MAPK phosphorylation, thereby mediating the Bcl-2/BAX/caspase-3 pathway." (PMID 37185746, 2023). "To examine whether AKR1B1 could inhibit tumor growth, we overexpressed AKR1B1 levels in human glioma cells by transfecting plasmid expression into the cells (denoted as AKR1B1-expressing glioma cells)." (PMID 37185746, 2023). "To explore whether AKR1B1 expression was inhibited in human glioma cells, we examined AKR1B1 mRNA levels in normal human brain tissues and glioma tissues." (PMID 37185746, 2023). "Additionally, AKR1B1-induced p38 MAPK phosphorylation and SB203580 reversed AKR1B1′s inhibitory effect on glioma cell proliferation." (PMID 37185746, 2023). "We further examined whether inhibiting AKR1B1 could promote glioma cell proliferation." (PMID 37185746, 2023). "Our data showed that AKR1B1 overexpression can induce p38 MAPK phosphorylation and inhibit glioma cell proliferation." (PMID 37185746, 2023). "Therefore, AKR1B1 may serve as a new therapeutic target for glioma therapy development." (PMID 37185746, 2023). "The effects of AKR1B1 overexpression or knockdown and those of AKR1B1-induced p38 MAPK phosphorylation and a p38 MAPK inhibitor (SB203580) on glioma cell proliferation were determined using an MTT assay and Western blot, respectively." (PMID 37185746, 2023). "Therefore, AKR1B1 may be a promising candidate for glioma treatment." (PMID 37185746, 2023). "High expression of AKR1B1 and NORAD was seen in glioma cells." (PMID 39055885, 2024). "In the mechanism of AKR1B1-induced cancer cell death, AKR1B1 might activate the p38 MAPK signaling pathway in glioma cells." (PMID 37185746, 2023).
prostate carcinoma (4 papers, 2019 to 2024). A carcinoma that arises from epithelial cells of the prostate gland. "Although AKR1B1 has also been found to be less expressed in prostate tumors, its role in prostate cancer remains unknown." (PMID 38173042, 2024). "In adrenocortical carcinomas and prostate cancer, AKR1B1 expression is decreased, but the mechanism and function remain unknown." (PMID 37185746, 2023). "Both members of the aldo-keto reductases (AKRs) family, AKR1B1 and AKR1B10, are over-expressed in various type of cancer, making them potential targets for inflammation-mediated cancers such as colon, lung, breast, and prostate cancers." (PMID 35807227, 2022).
triple-negative breast carcinoma (4 papers, 2023 to 2025). An invasive breast carcinoma which is negative for expression of estrogen receptor (ER), progesterone receptor (PR), and human epidermal growth factor receptor 2 (HER2). "We also observed that AKR1B1 overexpression promoted metastasis in the 4T1 orthotopic model of triple-negative breast cancer." (PMID 37780210, 2023). "Epalrestat, an aldo-keto reductase family 1 member B1 (AKR1B1) inhibitor, is in a Phase II study against triple-negative breast cancer (TNBC)." (PMID 37370809, 2023).
acute kidney injury (3 papers, 2012 to 2024). Sudden and sustained deterioration of the kidney function characterized by decreased glomerular filtration rate, increased serum creatinine or oliguria. "Consequently, AKR1B1 holds promise as a target for treating sepsis-associated acute kidney injuries." (PMID 38188141, 2024). "RT-qPCR validated miRNA and mRNAs included IGFBP2 (respiratory system); MMP9 and PDE4B (nervous system); PPARG (cardiovascular system); AKR1B1, ANXA1, and LNC2/NGAL (acute kidney injury); GFER/ALR (liver); and miR-30c-3p (coagulopathy)." (PMID 34573990, 2021).
adrenocortical carcinoma (3 papers, 2020 to 2025). "However, AKR1B1 expression has been demonstrated to be reduced in adrenocortical carcinoma (ACC), being less than adrenocortical adenomas and Cushing's hyperplasia." (PMID 32633024, 2020). "More GMRGs, including diacylglycerol kinase beta (DGKB), diacylglycerol kinase iota (DGKI), acylglycerol kinase (AGK), aldo-keto reductase family 1 member B1 (AKR1B1), and aldehyde dehydrogenase 9A1 (ALDH9A1), exhibited more CNV amplifications in adrenocortical carcinoma (ACC), KICH, OV, and UCS." (PMID 40137171, 2025).
alcoholic liver diseases (3 papers, 2019 to 2022). A disorder caused by damage to the liver parenchyma due to alcohol consumption. "In addition, the inhibition of AKR1B1 attenuated alcoholic liver disease by activating AMPK and modulating oxidative stress." (PMID 34356319, 2021). "In addition, ginseng Huang jiu could improve alcoholic liver disease by regulating the GSTP1, HRAS, AKR1B1, GSTA1, Androgen receptor (AR), GSR, and LDHB genes through bioinformatics analysis." (PMID 36034901, 2022).
cervical carcinoma (3 papers, 2014 to 2024). A carcinoma arising from either the exocervical squamous epithelium or the endocervical glandular epithelium. "In vitro studies have shown that AKR1B1-deficient cervical cancer cell lines exhibit lower proliferation, migration, and invasion than nonmanipulated cells." (PMID 35508982, 2022). "AKR1B1 was also linked to doxorubicin and cisplatin resistance in HeLa cervical carcinoma cells because an AKR1B1 inhibitor enhanced the cytotoxic effects of these anticancer agents." (PMID 24648844, 2014). "Epalrestat has been reported to suppress the proliferation and migration of HeLa cervical cancer cells by inhibiting AKR1B1." (PMID 39055885, 2024). "Interestingly, epalrestat also produced the same effect as AKR1B1 knockout suggesting its therapeutic potential in cervical cancer." (PMID 39055885, 2024). "The latest research has shown that targeting aldo–keto reductase family one member B1 (AKR1B1), which is highly expressed in several tumors and correlates with tumor growth, could benefit cervical cancer." (PMID 35508982, 2022).
colon adenocarcinoma (3 papers, 2015 to 2025). "IF‐based double staining experiments using colon adenocarcinoma tissues confirmed that AKR1B1 was indeed expressed by CD163 positive M2 macrophages." (PMID 40396420, 2025). "Stromal cells, primarily subepithelial macrophages, were seen to stain positively for AKR1B1 in non‐neoplastic colon mucosa, whereas the stroma of colon adenocarcinoma had widespread positivity." (PMID 40396420, 2025). "A cluster of 13 CpG loci (11 genes) were identified that displayed differential methylation in colon adenocarcinoma (COAD) (N = 289) compared to normal colon tissues (N = 38): ZNF671, TWIST1 (two CpG loci), TMEFF2, TM6SF1, GAS7, MAL, HIN1 (two CpG loci; SCGB3A1), COL6A2, AKR1B1, GPX7, ARHGEF7)." (PMID 34903270, 2021).
diabetic eye disease (3 papers, 2012 to 2023). A group of disorders affecting the eye in patients with diabetes mellitus. "The overexpression of AKR1B1 is closely associated with inflammatory mediators, and diabetic eye disease." (PMID 37308949, 2023). "Therefore, we propose that β-glucogallin would inhibit free glucose binding at the active site of AKR1B1, preventing sorbitol production under hyperglycemic conditions such as in patients suffering from diabetic eye disease." (PMID 22485126, 2012).
endometrial cancer (3 papers, 2020 to 2022). Primary or metastatic malignant neoplasm involving the endometrium (mucous membrane that lines the endometrial cavity). "AKR1B1 expression in endometrial cancer has been reported to be decreased and correlated negatively with body mass index (BMI) suggesting a decreased PGF2a formation." (PMID 32633024, 2020). "Thus, AKR1B1 could be involved in the initiation of endometrial cancer through modulating inflammation." (PMID 32633024, 2020). "The roles of aldo-keto reductase family 1 member B1 (AKR1B1) and B10 (AKR1B10) in the pathogenesis of many cancers have been widely reported but only briefly studied in endometrial cancer." (PMID 34298614, 2021).
lymph node metastasis (3 papers, 2022 to 2026). "Remarkably, SMAD4 and AKR1B1 hypermethylation exhibited a significant association with invasive duct carcinoma (IDC), particularly in early stages, high grades, and cases with lymph node metastasis." (PMID 41760667, 2026). "AKR1B1 is closely related to age, vascular and neural invasion, lymph node metastasis, and the TNM stage of GC." (PMID 37751590, 2023).
Sepsis (3 papers, 2014 to 2024). Sepsis is defined as life-threatening organ dysfunction caused by a dysregulated host response to infection. "The identification of AKR1B1 as a different therapeutic target not only sheds light on the pathogenesis of SA-AKI but also introduces a novel avenue for clinical prevention in sepsis-associated complications." (PMID 38188141, 2024). "Given its involvement in inflammatory diseases, such as sepsis, AKR1B1 has garnered significant research interest in recent years." (PMID 38188141, 2024). "As studies reporting on AKR1B1 and its involvement in sepsis are scarce, AKR1B1 was selected as the candidate molecule." (PMID 38188141, 2024).
serous ovarian cancer (3 papers, 2022). "In this study, we determined the binding of (±)KU and AKR1B1 on triple-negative breast and non-serous ovarian cancers." (PMID 36552555, 2022). "We evaluated the levels of AKR1B1 and AKR1B10 in 99 patients with high-grade serous ovarian cancer and their association with clinicopathological characteristics, survival, and response to chemotherapy." (PMID 35159076, 2022). "The upregulation of G6PD, AKR1B1, ITGAV, and TGFβ1 in OVCAR5 CBPR cells was also identified in the tumors of platinum-resistant compared to platinum-sensitive high grade serous ovarian cancer (HGSOC) patients." (PMID 36463238, 2022). "We used the RNA expression data of the genes AKR1B1 and AKR1B10 in the tissues of high-grade serous ovarian cancer (acquired by RNA-Seq and Expectation-Maximization (RSEM) algorithms with batch normalization) and clinical data from the TCGA Pan-Cancer Atlas study." (PMID 35159076, 2022). "We assessed the immunohistochemical levels of AKR1B1 and AKR1B10 in tissue paraffin sections from 99 patients with high-grade serous ovarian cancer (HGSC) and compared these levels with clinicopathological characteristics, survival, and response to chemotherapy." (PMID 35159076, 2022).